MMP11 (matrix metallopeptidase 11)
Description:
May play an important role in the progression of epithelial malignancies.
Synonyms: SL-3; ST3; STMY3
Tractability: Small molecule: it belongs to a druggable protein family. Antibody: UniProt places it where antibodies can reach, with high confidence; its Gene Ontology location is reachable by antibodies, with high confidence; UniProt predicts a signal peptide or a membrane-spanning region. PROTAC: a small molecule that binds it is known.
Target class: Metallo protease; Metallo protease M10A subfamily; Metallo protease MAM clan; Protease; Enzyme
Gene: Protein-coding gene on chromosome 22 (23,768,226 to 23,784,322, forward strand). Ensembl gene ENSG00000099953.
Subcellular location: Secreted, extracellular space, extracellular matrix
Subcellular location (Human Protein Atlas): Golgi apparatus; Cytosol; Predicted to be secreted
Pathways (Reactome):
Extracellular matrix organization: Activation of Matrix Metalloproteinases; Collagen degradation; Degradation of the extracellular matrix
Gene Ontology:
Molecular function: metalloendopeptidase activity; serine-type endopeptidase activity; metallopeptidase activity; peptidase activity; zinc ion binding
Biological process: collagen catabolic process; extracellular matrix disassembly; extracellular matrix organization; proteolysis
Cellular component: extracellular matrix; extracellular region; Golgi lumen
Genetic constraint (gnomAD): Loss-of-function variants: 26 observed, 46.52 expected, observed/expected ratio (o/e) 0.56, 90% interval 0.41 to 0.77. The upper end of that interval is the gene's LOEUF score, 0.77, which puts it in group 3 of 6, group 1 being the genes least tolerant of losing a copy. Missense variants: 563 observed, 631.89 expected, observed/expected ratio (o/e) 0.89, 90% interval 0.83 to 0.95. Synonymous variants: 243 observed, 260.52 expected, observed/expected ratio (o/e) 0.93, 90% interval 0.84 to 1.04.
Homologues: Orthologues: chimpanzee MMP11 (99% identical), macaque MMP11 (97% identical), dog MMP11 (87% identical), rabbit MMP11 (87% identical), guinea pig MMP11 (84% identical), pig MMP11 (83% identical), mouse Mmp11 (82% identical), rat Mmp11 (82% identical), tropical clawed frog mmp11 (60% identical), zebrafish mmp11a (52% identical), zebrafish mmp11b (52% identical), Caenorhabditis elegans zmp-3 (26% identical), and 4 more. Paralogues in human: MMP24 (37% identical), MMP14 (35% identical), MMP15 (35% identical), MMP25 (34% identical), MMP17 (34% identical), MMP16 (34% identical), MMP3 (32% identical), MMP2 (31% identical), MMP1 (31% identical), MMP10 (31% identical), MMP13 (30% identical), MMP9 (30% identical), and 11 more.
Diseases named in the same sentence as MMP11 in open-access papers:
MMP11 is named in the same sentence as 133 diseases in open-access papers, as found by Europe PMC text mining. Sharing a sentence is not in itself a finding about the gene and the disease. The quoted sentences say what the papers report.
breast carcinoma (121 papers, 1998 to 2026). "Given that MMP11 is differentially expressed in this cohort of early breast cancer, we sought to determine its association with classical tumor characteristics and prognostic markers." (PMID 38438841, 2024). "In conclusion, our study in early luminal breast cancer patients reveals that MMP-11 expression, predominantly seen in cancer-associated fibroblasts, is linked with tumor grade and uPA levels." (PMID 38438841, 2024). "While many studies associate MMP-11 expression with poor prognosis in breast cancer, few focus on early-stage cases." (PMID 38438841, 2024). "This analysis shows the potential of a combined stratification using Ki67 and MMP-11 expression to predict the risk of recurrence in early luminal breast cancers." (PMID 38438841, 2024). "Cellular genetic factors trigger the breakdown of adipocytes, which have more tissue around the developing breast cancer, resulting in a phenotype associated with an increase in cytokines and MMP-11, which attacks breast cancer and metastasis." (PMID 38956273, 2024). "A previous study showed that MMP11 is associated with various signalling pathways involved in tumour development in breast cancer and that high expression of MMP11 is associated with poor prognosis for patients." (PMID 37543577, 2023). "This study aims to explore the association between MMP-2, MMP-9, and MMP-11 expression with clinicopathologic features among breast cancer patients in Ethiopia." (PMID 37798646, 2023). "For example, for breast cancer, MMP-11 expression by ECs was associated with a shorter relapse-free survival, whereas TIMP-3 expression was linked to the small appearance of distant metastasis." (PMID 36139572, 2022). "Several studies have shown a significant association between stromal MMP-11 or -14 expression and poor prognosis in breast cancer." (PMID 36741729, 2022). "Previous studies demonstrated that high MMP-11 was associated with poor prognosis in the breast cancer." (PMID 34038440, 2021). "Many studies have shown that high MMP-11 expression is associated with poor clinical outcomes in lung cancer, colorectal cancer, hepatocellular carcinoma, osteosarcoma, prostate cancer and breast cancer." (PMID 34038440, 2021). "Meanwhile, ROC curve analysis was conducted to assess the potential of circ-MMP11 as a diagnostic marker for breast cancer patients." (PMID 34295807, 2021). "High MMP-11 expression was associated with worse survival rate in breast cancer from HUGH cohort and TCGA data (all p < 0.05)." (PMID 34038440, 2021). "Apart from that, the repression role of circ-MMP11 deficiency on tumor growth and lapatinib resistance of breast cancer cells was verified in vivo." (PMID 34295807, 2021). "In particular, the expression of MMP11 in tumor-infiltrating immune cells was highly associated with both distant metastasis development and high inflammatory profile in breast cancer." (PMID 33396463, 2020). "In the context of breast cancer, MMP11 is a TME component expressed by cancer-associated fibroblasts (CAFs) in the tumor center and by cancer-associated adipocytes (CAAs) at the tumor invasive front." (PMID 32825455, 2020). "Matrix metalloproteinase-11 (MMP11), also called stromelysin-3, is a protein secreted by stromal cells during breast cancer invasion, and increased MMP11 levels have been associated with poor outcome in cancer patients." (PMID 32825455, 2020). "Studies suggested that genes, such as MMP2, MMP9, MMP11 and uPA, were found to be associated with breast cancer progression, angiogenesis and metastasis." (PMID 28388580, 2017). "Specifically, increased levels of MMP11 in human and mouse breast cancers are associated with increased metastasis and poor patient prognosis." (PMID 27141287, 2016). "IL-33 and sST2 were significantly associated with MMP-11 or PDGF-C which indicated poor prognosis of breast cancer patients." (PMID 26456994, 2015).
breast carcinoma (continued). "Here, our ELISA data showed an elevation of MMP-11 in sera of breast cancer patients and a significant association between MMP-11 and IL-33 or sST2 concentration was found." (PMID 26456994, 2015). "This resulted in the identification of two upregulated genes (DPEP1 and MMP11) as mutated in colon cancer and another three protease genes mutated in breast cancer (TMPRSS3, ADAM12 and MMP10)." (PMID 24243807, 2013). "The MMP-11 (stromalysin-3) is preferential expressed by peritumour stromal cells and high levels of MMP-11 were associated with tumour progression and poor prognosis in breast cancer." (PMID 20160732, 2010). "MT1-MMP (MMP-14) and stromelysin-3 (MMP-11) are two members of the MMP family of proteolytic enzymes that have been specifically implicated in breast cancer progression." (PMID 15272933, 2004). "Increased MMP11 expression in the tumor microenvironment (cancer-associated adipocytes and cancer-associated macrophages) was documented in several invasive cancers, including breast cancer." (PMID 37445827, 2023). "High expression of MMP-11 in TAMs is associated with poor outcomes in breast cancer patients." (PMID 36906534, 2023). "High MMP11 expression has been found associated with poor survival of breast cancer patients." (PMID 37238942, 2023). "Tumor growth was studied in mice either deficient (Loss of Function-LOF) or overexpressing MMP11 (Gain of Function-GOF) crossed with a transgenic model of breast cancer induced by the polyoma middle T antigen (PyMT) driven by the murine mammary tumor virus promoter (MMTV) (MMTV-PyMT)." (PMID 32825455, 2020). "The role of adipokines was demonstrated by Dirat et al141 who reported increased invasiveness of both human and murine breast cancer cells associated with overexpression of proteases, including MMP-11, and pro-inflammatory cytokines (IL-6, IL-1β), when cocultured with adipocytes." (PMID 29104428, 2017). "Levels of MMP11 expression may be used to identify patients at greatest risk for cancer recurrence, in breast carcinoma, pancreatic tumors and colon cancer." (PMID 24564996, 2014). "Other high-ranking genes include MMP11, which is well documented in the literature as playing a pivotal role in breast cancer, showing high expression levels in early luminal subtypes." (PMID 41363728, 2026). "MMP11, another matrix metalloproteinase, is highly expressed in the tumor stroma of breast cancer and plays a key role in promoting tumor invasion and metastasis through the remodeling of the extracellular matrix." (PMID 40565055, 2025). "The authors concluded that MMP-11 expression was higher in breast cancer tissues than in benign tumors." (PMID 40266038, 2025). "The results revealed that MMP11+ mCAFs predominantly overlapped with FN1+ CAFs in breast cancer, COL11A1+ CAFs in colorectal cancer, and CTHRC1+ CAFs in lung adenocarcinoma." (PMID 40552583, 2025). "Analysis revealed that the proportion of MMP11+ mCAFs varied significantly across different stages of gastric cancer, breast cancer, and lung adenocarcinoma." (PMID 40552583, 2025). "Pan‐cancer analysis revealed that MMP11+ mCAFs are present across various cancer types, including breast cancer, lung adenocarcinoma, gastric cancer, and colorectal cancer." (PMID 40552583, 2025). "In breast cancer, CAAs express high levels of MMP11, promoting cancer cell invasion into surrounding tissues." (PMID 40841364, 2025). "Pan‐cancer analysis further revealed that MMP11+ mCAFs are prevalent across multiple cancers, including breast cancer, lung adenocarcinoma, gastric cancer, and colorectal cancer, all correlated with poor prognosis." (PMID 40552583, 2025). "Comprehensive analyses supported miR-98’s important role in regulating tumor growth, invasion, and angiogenesis by down-regulating ALK4 and MMP11, as well as its potential predictive value as a biomarker in breast cancer patients." (PMID 38872210, 2024).
breast carcinoma (continued). "Over the years, extensive studies have shed light on the prognostic significance of MMP-11 in breast cancer and other malignancies." (PMID 38438841, 2024). "Our study reinforces the idea that MMP-11 plays a pro-tumoral role in hormone-receptor positive breast cancers, the predominant subtype of breast cancers." (PMID 38438841, 2024). "Of note, MMP-11 expression was detected in these CAFs across all three molecular subtypes of breast cancer, with a notable prevalence in HER2-positive tumors and, to a lesser extent, in estrogen receptor-positive cancers." (PMID 38438841, 2024). "In particular, MMP-11 is one of a panel of 21 genes used to predict distant recurrence of breast cancer." (PMID 38438841, 2024). "Although these findings are based on RNA expression rather than protein levels, they still underscore the prognostic significance if MMP-11 in luminal breast cancer, suggesting of its potential as a biomarker, even when different methodologies are employed." (PMID 38438841, 2024). "MMP11 overexpression in macrophages promotes the proliferation and migration of breast cancer cells and monocyte recruitment." (PMID 38835896, 2024). "In a follow-up study, an effort was put to unravel the role of such MMP11-driven metabolic alterations in the specific context of breast cancer and tumor progression." (PMID 37445827, 2023). "Upon the binding of NF-κB/p65 to the promoter regions of EMT transcription factors, MMP11 is activated resulting in the induction of the EMT process in human breast cancer cells." (PMID 37543577, 2023). "MMP11 was initially identified in our laboratory back in 1990 as a factor secreted by stromal cells of breast carcinomas." (PMID 37445827, 2023). "MMP11 was also increased in both the stroma of mammary carcinomas, in whole tumours of metastatic canine mammary carcinomas compared to non-metastatic ones, and its expression was correlated with invasiveness in human breast cancer." (PMID 37391533, 2023). "Several studies have investigated the association between clinicopathological features of breast cancer with MMP-2, MMP-9, and matrix metallopeptidases − 11 (MMP-11) expression." (PMID 37798646, 2023). "There is also a positive correlation between the expression of MMP-2, MMP-9, and MMP-11 and breast cancer prognosis." (PMID 37798646, 2023). "Matrix metalloproteinase-11 (MMP11), a member of MMPs, also known as stromelysin-3, was first identified in breast cancer." (PMID 36756152, 2023). "The MMP-11 expression levels were significantly higher in breast cancer cases than in benign breast tumors (P = 0.012)." (PMID 37798646, 2023). "The significance of TAMs’ specialized function in breast cancer becomes evident through the secretion of MMP11, which plays a critical role in facilitating the migration of breast cancer cells that are HER2-positive." (PMID 38332915, 2023). "MMP-11 was also found to be expressed in ECs from breast cancer samples, and MMP-11 expression in ECs was significantly correlated with shorter relapse-free and overall survival (OS)." (PMID 36741729, 2022). "This is certainly the case for MMP19, involved in the development of T cells in mice; MMP11, related to several cytokines in breast cancer cells; and ADAMTS1, a known regulator of the inflammatory response." (PMID 35903133, 2022). "Macrophage-CM also increased MMP-3 and MMP-11 expression by adipocytes in adipocyte–breast cancer co-culture." (PMID 36551185, 2022). "We identified that Pictilisib and AZ960 affected breast cancer cell lines with high MMP-11 expression." (PMID 34038440, 2021). "Based on Kaplan–Meier analysis, the LR breast cancer patients in the low circ-MMP11 level group had a higher survival rate than those in the high circ-MMP11 level group." (PMID 34295807, 2021). "The cytoplasmic expression of circ-MMP11 in breast cancer cells and LR breast cancer cells indicated the post-transcriptional regulatory mechanism of circ-MMP11 in breast cancer." (PMID 34295807, 2021).
breast carcinoma (continued). "In this study, our data showed that circ-MMP11 was upregulated in the lapatinib-resistant (LR) breast cancer tissues and cells." (PMID 34295807, 2021). "In view of the high expression of circ-MMP11 in LR-resistant breast cancer cells, we knocked down circ-MMP11 in MDA-MB-231/LR and MCF-7/LR cells." (PMID 34295807, 2021). "First of all, to investigate the role of circ-MMP11 on lapatinib resistance in breast cancer, its expression level was detected by RT-qPCR assay." (PMID 34295807, 2021). "We found that pictilisib and AZ960 effectively inhibited the breast cancer cell lines with high MMP-11 expression." (PMID 34038440, 2021). "The biological role of circ-MMP11 on breast cancer tumor growth and drug resistance was detected by the xenograft tumor model in vivo." (PMID 34295807, 2021). "As a new circRNA, circ-MMP11 has been presented the carcinogenesis by boosting cell proliferation and migration in breast cancer." (PMID 34295807, 2021). "Disease-free and disease-specific survival analyses according to MMP-11 in 226 breast cancer patients (HUGH cohort)." (PMID 34038440, 2021). "In a recent report, circ-MMP11 (hsa_circ_0062558) functioned as a competitive endogenous RNA (ceRNA) of miR-1204 to accelerate the progression of breast cancer." (PMID 34295807, 2021). "These mentioned results unraveled that circ-MMP11 knockdown improved lapatinib sensitivity through interacting with miR-153-3p in LR breast cancer cells." (PMID 34295807, 2021). "MMP11 has been characterized extensively for its role in breast cancer and has been shown to be a predictive factor for tumor invasiveness, hence serving as positive control here." (PMID 34149812, 2021). "In other words, we were first demonstrated that circ-MMP11 conferred lapatinib resistance in LR breast cancer cells in vitro and in vivo." (PMID 34295807, 2021). "And, AZ960 had meaningful effect (r = -0.314) in breast cancer cell lines exhibiting high MMP-11 expression." (PMID 34038440, 2021). "Nevertheless, little is known about the value of circ-MMP11 in drug-resistance and progression of breast cancer." (PMID 34295807, 2021). "On the basis of the GDSC data, we analyzed drug sensitivity patterns in 50 breast cancer cell lines with high MMP-11 expression based on 172 drugs." (PMID 34038440, 2021). "Previous studies have shown that overexpression of MMP-11 is associated with a large tumor size, lymph node involvement, high histologic grade, estrogen receptor (ER), HER2, and poor survival in breast cancers." (PMID 34038440, 2021). "This study is designed to explore the role and mechanism of circ-MMP11 in lapatinib resistance in breast cancer." (PMID 34295807, 2021). "We evaluated the sensitivity to pictilisib and AZ960 in breast cancer cell lines with high MMP-11 expression and those with low MMP-11 expression." (PMID 34038440, 2021). "In the breast cancer data from the TCGA database, MMP-11 was more highly expressed in primary tumors than in normal tissues." (PMID 34038440, 2021). "Circular RNA (circRNA) circ-MMP11 has been reported to be promoting the progression of breast cancer." (PMID 34295807, 2021). "Along with in vivo studies, pictilisib- and/or AZ960-based clinical trials in breast cancer patients with high MMP-11 expression are needed in the future." (PMID 34038440, 2021). "Functionally, the downregulation of miR-153-3p partly reversed circ-MMP11 knockdown-mediated enhancement in lapatinib sensitivity, and decrease cell growth and metastasis of LR breast cancer cells." (PMID 34295807, 2021). "Lapatinib resistance is promoted by circ-MMP11 in breast cancer cells, and mechanically circ-MMP11 regulates ANLN expression by sponging miR-153-3p." (PMID 35070998, 2021). "This threshold allowed the identification of a subgroup of breast cancer patients (n = 14, 25.9% of total BC-patients) with significantly higher MMP11 gene expression." (PMID 33396463, 2020).